SEC14L4 (SEC14 like lipid binding 4)
Description:
Probable hydrophobic ligand-binding protein; may play a role in the transport of hydrophobic ligands like tocopherol, squalene and phospholipids.
Synonyms: TAP3; dJ130H16.5
Tractability: Small molecule: a structure with a bound ligand is known.
Gene: Protein-coding gene on chromosome 22 (30,488,902 to 30,505,711, reverse strand). Ensembl gene ENSG00000133488.
Subcellular location (Human Protein Atlas): Vesicles; Cytosol
Gene Ontology:
Molecular function: protein binding
Cellular component: cytoplasm
Genetic constraint (gnomAD): Loss-of-function variants: 36 observed, 47.94 expected, observed/expected ratio (o/e) 0.75, 90% interval 0.57 to 0.99. The upper end of that interval is the gene's LOEUF score, 0.99, which puts it in group 4 of 6, group 1 being the genes least tolerant of losing a copy. Missense variants: 426 observed, 502.36 expected, observed/expected ratio (o/e) 0.85, 90% interval 0.78 to 0.92. Synonymous variants: 201 observed, 204.24 expected, observed/expected ratio (o/e) 0.98, 90% interval 0.88 to 1.11.
Homologues: Orthologues: chimpanzee SEC14L4 (99% identical), macaque SEC14L4 (93% identical), guinea pig SEC14L4 (86% identical), dog SEC14L4 (83% identical), mouse Sec14l4 (83% identical), rat Sec14l4 (81% identical), pig SEC14L4 (64% identical), zebrafish sec14l8 (58% identical), zebrafish sec14l7 (55% identical), Drosophila melanogaster CG13893 (32% identical), Caenorhabditis elegans T23G5.2 (30% identical), Caenorhabditis elegans ctg-1 (29% identical), and 3 more. Paralogues in human: SEC14L6 (77% identical), SEC14L2 (70% identical), SEC14L3 (69% identical), SEC14L1 (33% identical), SEC14L5 (33% identical), TTPA (17% identical).
Diseases named in the same sentence as SEC14L4 in open-access papers:
SEC14L4 is named in the same sentence as 4 diseases in open-access papers, as found by Europe PMC text mining. Sharing a sentence is not in itself a finding about the gene and the disease. The quoted sentences say what the papers report.
anemia (1 paper, 2022). A reduction in the number of red blood cells, the amount of hemoglobin, and/or the volume of packed red blood cells. "Although mutations in G6PD and HBA2 are associated with anemia and human disease, SEC14L4 and MYO9B are not previously known to affect RBC function." (PMID 34793330, 2022).
G6PD deficiency (1 paper, 2022). An X-linked genetic condition caused by alterations in the gene G6PD that result in moderately to severely decreased activity levels of the enzyme glucose-6-phosphate dehydrogenase. "Donor G6PD deficiency and polymorphisms in SEC14L4 were associated with increased transfusion requirements in the subsequent 48 hours." (PMID 34793330, 2022). "Donor G6PD deficiency and polymorphisms in SEC14L4, HBA2, and MYO9B genes were associated with decreased hemoglobin increments." (PMID 34793330, 2022).
Parkinson disease (1 paper, 2020). A progressive degenerative disorder of the central nervous system characterized by loss of dopamine producing neurons in the substantia nigra and the presence of Lewy bodies in the substantia nigra and locus coeruleus. "The loci within these eQTL scores have been reported to regulate expression of genes involved in various brain-related processes and disorders, such as neurite outgrowth and Parkinson’s disease (DCAKD, SLC35A4, SEC14L4, SRA1, NMT1, CPNE1, PLEKHM1, UBE3C)." (PMID 32066731, 2020).
SEC14L4 also shares sentences with these, for which no sentence is quoted: asthma (1 paper).